TPH1 (tryptophan hydroxylase 1)
Diseases named in the same sentence as TPH1 in open-access papers (continued):
Sharing a sentence is not in itself a finding about the gene and the disease.
cancer (continued). "Thus, it is amenable to develop a radiolabeled tryptophan to monitor in vivo expression and activity of IDO, LAT1, and TPH1 as well as to assess therapeutic response after selective inhibitors of IDO, LAT1, and TPH1 in cancer treatments." (PMID 25136592, 2014). "Presumably, these advantages explain why TPH1 expression does not simply continue to decline to zero in advanced cancers, and is commonly elevated in the most highly-transformed cancer cells." (PMID 19903352, 2009).
psychiatric disorder (11 papers, 2005 to 2025). A disorder characterized by behavioral and/or psychological abnormalities, often accompanied by physical symptoms. "Thus, one may assume that TPH1 A218C/A779C polymorphisms are associated with increased susceptibility to psychiatric disorders in general, which in turn are characterized by an increased incidence of suicide." (PMID 27721799, 2016). "This suggests that TPH1 might be associated with an increased risk of psychiatric disorders in general and not specifically with suicide." (PMID 40282388, 2025).
infection (10 papers, 2008 to 2024). The state of being infected such as from the introduction of a foreign agent such as serum, vaccine, antigenic substance or organism. "For example, tryptophan 5-hydroxylase 1 (Tph1)−/− mice, deficient in serotonin production, exhibit a reduction in the migration of neutrophils to the inflammatory site upon infection stimulation due to impaired diapause." (PMID 39736771, 2024). "Finally, we analysed tph-1/tryptophan hydroxylase induction upon pathogenic infection." (PMID 34232959, 2021). "In contrast, 5-HT repletion increased survival, restricted fungal growth, and ameliorated lung pathology and inflammatory cytokine production, thus improving resistance to infection in Tph1−/− mice." (PMID 37717018, 2023). "In contrast, Propionibacteriaceae (Cutibacterium genus), Alcaligenaceae, and Enterobacteriaceae expanded early followed by the expansion of Sphingomonadaceae (Sphingomonas genus) late in infection in Tph1−/− littermates." (PMID 37717018, 2023). "To directly assess the contribution of the local vs the distal microbiota to the Trp metabolism in infection, we did criss-cross experiments in which the lung or fecal microbiota from Tph1+/+ was transplanted into Tph1−/− littermates and vice versa." (PMID 37717018, 2023). "In particular, transplantation of Tph1+/+ lung microbiota restored resistance to infection and decreased inflammation in Tph1−/− mice while the opposite was true in Tph1+/+ littermates transplanted with Tph1–/– lung microbiota." (PMID 37717018, 2023). "Accordingly, significant increase levels of the 5-HTP and 5-HT were observed in the lung of Tph1+/+ mice early in infection to decline thereafter." (PMID 37717018, 2023). "In the present study, both cat-2 and tph-1 mutants succumbed faster than the WT to S. Typhimurium DT104 infection." (PMID 33134188, 2020). "In the present work, we demonstrated that the Tph1/5-HT pathway, by critically regulating Trp partitioning in the lung, profoundly affects the local innate and adaptive immune response in infection, thus confirming the critical role of Trp in regulating lung immunity and inflammation." (PMID 37717018, 2023). "To determine whether infection with M. nematophilum altered transcription of tph-1 we propagated animals stably expressing a tph-1p::DSRED transgene on small bacterial lawns contaminated with virulent, or avirulent, forms of M. nematophilum." (PMID 24348250, 2013). "Therefore, in settings where there is no overlap between Brugia and Wuchereria infections, the TC8100/tph-1 multiplex assay could be used to evaluate infection and infectivity rates simultaneously." (PMID 18560545, 2008). "NSY-1-SEK-1 p38 signaling promotes the transcription of antimicrobial genes, such as nlp-29, in the hypodermis and tph-1, the serotonin synthesis gene, in ADF in response to infection." (PMID 37310929, 2023). "This suggests that the Tph1/5-HT, by sustaining the IDO1 and restraining AhR activation, exerts a critical control upon the dynamic activation of the two pathways in infection." (PMID 37717018, 2023). "For example, in tryptophan metabolism, the expression of tryptophan hydroxylase 1 (TPH1, FC = 61) and tryptophan 2,3-dioxygenase (TDO2, FC = 4.2) was upregulated, potentially affecting tryptophan biosynthesis after CH60 infection." (PMID 30197639, 2018). "Combined, these data suggest that GPB-1 function is essential for EGL-30 Gqα signaling during pathogen infection, and an EGL-30- and TIR-1-independent GPB-1 function in the OCR-2 signaling pathway directs baseline ADF tph-1 expression." (PMID 26402365, 2015). "Using cell specific rescue experiments we have shown that expression of TPH-1 (and therefore serotonin synthesis) in ADF is required to suppress the immune response to infection by M. nematophilum." (PMID 24348250, 2013).
infection (continued). "In the present study, both tph-1 and cat-2 mutants succumbed faster than the WT to S. Typhimurium DT104 infection, suggesting a positive role of both serotonin and dopamine in the nematode defense against the pathogen infection." (PMID 33134188, 2020). "Mutants tph-1 and cat-2 both succumbed faster than the WT after DT104 infection (P ≤ 0.05)." (PMID 33134188, 2020). "Our cell-specific rescue experiments, combined with the report that Gqα EGL-30 function in AWC and AWB neurons is necessary and sufficient for PA14-induced ADF tph-1 upregulation, argue that GPB-1 is a regulator for EGL-30 signaling in AWC and AWB that relay infection cues to ADF." (PMID 26402365, 2015). "Consistent with Gβ as a regulator of Gα signaling, yz71 mutants failed to upregulate ADF tph-1::gfp during PA14 infection, and the gpb-1(g) transgene rescued the PA14 sensitivity." (PMID 26402365, 2015). "To identify and discern the GPB-1 action sites for basal and pathogen-induced tph-1 expression, we generated transgenic lines expressing gpb-1 cDNA in defined cells and tested their ability to rescue ADF tph-1::gfp expression in yz71 mutants under optimal conditions and during PA14 infection." (PMID 26402365, 2015). "Secondly, we expressed RE::EGL-30* in tph-1(mg280), or tph-1(n4622), animals in the absence of infection." (PMID 24348250, 2013). "Together these results indicate that the changes in TPH-1 expression levels we observed were largely due to reduced contact with the bacterial lawn when it was contaminated with virulent M. nematophilum and not due to infection." (PMID 24348250, 2013). "To determine whether the enhanced Dar phenotype of tph-1(mg280) and tph-1(n4622) was due to a decrease in serotonin synthesis we grew animals lacking tph-1 on 0.05% M. nematophilum infection plates supplemented with exogenous serotonin." (PMID 24348250, 2013). "To determine whether the enhanced immune response of tph-1(mg280) and tph-1(n4622) was due to a decrease in serotonin synthesis we grew animals lacking tph-1 on infection plates supplemented with serotonin." (PMID 24348250, 2013).
gastrointestinal disorders (4 papers, 2020 to 2024). "Consistently, in gastrointestinal diseases such as IBS and IBD, dysregulation of TPH1 and SERT expression has been repeatedly reported, further reinforcing the correlation between chronic stress-induced changes in 5-HT induced by chronic stress and the susceptibility to gastrointestinal disorders." (PMID 39247815, 2024).
metabolic disorders (4 papers, 2010 to 2025). "A growing body of evidence shows associations of genetic variants of TPH1/2, SERT, and 5-HTRs with metabolic diseases such as obesity, T2D, and MAFLD." (PMID 39926388, 2025).
bacterial infection (2 papers, 2015 to 2021). "To discern and define the role of GPB-1 in steady state and stress-induced 5-HT synthesis, we measured tph-1::gfp in yz71 mutants under optimal conditions and two well-established aversive conditions, dauer formation and pathogenic bacterial infection." (PMID 26402365, 2015). "Pathogenic bacterial infection is another established aversive paradigm inducing ADF tph-1 upregulation." (PMID 26402365, 2015). "DAF-19, the only RFX TF in C. elegans, is required for developmental tph-1/tryptophan hydroxylase expression as well as to mediate tph-1/tryptophan hydroxylase transcriptional increase upon different insults including bacterial infection or cilia morphology defects." (PMID 34232959, 2021).
renal diseases (1 paper, 2019). "We hypothesized that upregulation of endogenous 5-MTP by TPH-1 exerts favorable therapeutic effects on renal diseases." (PMID 30931940, 2019).
TPH1 also shares sentences with these, for which no sentence is quoted: gastrointestinal disease (3 papers); metabolic syndrome (3); migraine (3); pulmonary hypertension (3); acute pneumonia (2); Alzheimer disease (2); asthma (2); autism (2); emotional dysregulation (2); Hyperinsulinemia (2); mental disorder (2); neurologic disorders (2); non-alcoholic fatty liver disease (2); triple-negative breast carcinoma (2); acute myeloid leukemia (1); adenoma (1); airway hyperresponsiveness (1); allergic rhinitis (1); Anorexia (1); autism spectrum disorder (1); bladder cancer (1); Borderline personality disorder (1); brain diseases (1); candidiasis (1); carcinoid heart disease (1); cardiac failure (1); cerebrovascular disease (1); chronic obstructive pulmonary disease (1); colorectal tumor (1); cystic fibrosis (1).
A further 30 diseases each share a sentence with TPH1 in 1 paper.